USP6 (ubiquitin specific peptidase 6)
Diseases named in the same sentence as USP6 in open-access papers (continued):
Sharing a sentence is not in itself a finding about the gene and the disease.
tumor (42 papers, 2014 to 2026). "Gain- and loss-of-function experiments of miR-130a and USP6 were conducted in nude mice to assess UM cell motility, invasion, and tumor formation." (PMID 40348771, 2025). "A significant percentage of ABCs (70%) is now recognized as a neoplasm associated with genetic rearrangements caused by recurrent chromosomal translocations involving ubiquitin-specific peptidase 6 (USP6)." (PMID 41462855, 2025). "Previously, it was believed to occur as a reaction to trauma or as a reactive lesion caused by an underlying vascular event, but in recent years, it has been considered a true neoplasm caused by rearrangement of the ubiquitin-specific peptidase 6 (USP6) gene." (PMID 39312383, 2024). "In recent years, a growing number of molecular genetic studies (including research from our group) have expanded the families of USP6-associated neoplasms." (PMID 36727055, 2022). "Intriguingly, according to our study and previous literature, almost all of the USP6-associated neoplasms with bone metaplasia adopt COL1A1 as the fusion partner, including MO, FOPD, ST-ABC and FO." (PMID 36727055, 2022). "Notably, in USP6-associated neoplasms, although an increasing number of partner genes have been identified, there is a preference for these partner genes in different tumor subtypes." (PMID 36727055, 2022). "Notably, USP6-associated neoplasms are characterized by proliferative myofibroblasts/fibroblasts with or without metaplasia of osteoid components." (PMID 36727055, 2022). "Thereafter, these two entities were included as USP6-associated neoplasms." (PMID 36727055, 2022). "Ubiquitin-Specific Protease 6 (USP6) exhibits a dual role functioning both as a tumor promoter and a tumor suppressor." (PMID 40348771, 2025). "Xenografting CRISPR cells into immunodeficient mice indicated a crucial role for JAK1 and STAT3 in USP6-induced tumor development." (PMID 40348771, 2025). "In recent years, growing numbers of molecular genetic investigations have increased the families of neoplasms related to USP6." (PMID 40348771, 2025). "The contrasting roles of USP6 as both a tumor suppressor and promoter underscore the complexity of its function in cancer biology." (PMID 40348771, 2025). "USP6 enhances the immune response against tumors, creating an immunostimulatory microenvironment important for effective anti-tumor activity." (PMID 40348771, 2025). "Samples were assessed using an RNA-based targeted sequencing panel that targeted genes, such as USP6, frequently altered in neoplasia." (PMID 40348771, 2025). "Xenografting these cells into NOG-SCID mice showed that DKK1 expression greatly suppressed USP6-dependent tumor growth." (PMID 40348771, 2025). "Understanding the role of USP6 gene rearrangements in cranial fasciitis is a major step forward in treating this uncommon pediatric tumor." (PMID 40348771, 2025). "When USP6 is overexpressed due to genetic rearrangements or fusions, contributes to tumor formation." (PMID 40348771, 2025). "In current opinion, however, it is regarded as a true neoplasm due to the rearrangement of the ubiquitin-specific peptidase 6 (USP6) gene." (PMID 38335421, 2024). "Both the sarco-sphere model as well as the corresponding tumor tissue harbored an in-frame EIF5A::USP6 fusion in chromosome 17, homozygous losses of CDKN2A/B and ATRK, a truncation in the NOTCH1 gene and a TCF3::SLC39A3 rearrangement." (PMID 37951844, 2024). "Strikingly, USP6 reversed this, restoring both the abundance and activation of circulating NK cells back to levels in control non–tumor-bearing mice." (PMID 37615015, 2023). "USP6’s tumor-inhibitory function was confirmed in a distinct mouse strain with intact innate immunity, RAG2−/−." (PMID 37615015, 2023). "Molecular detection demonstrated evidence of ubiquitin-specific peptidase 6 (USP6) gene rearrangement in this tumor." (PMID 36741963, 2023).
tumor (continued). "Enforced overexpression of miR-130a impaired cell migration and invasion in vitro by inducing downregulation of USP6 (ubiquitin specific peptidase 6) and inactivation of Wnt/β-catenin pathway; moreover, miRNA overexpression inhibited tumor growth in vivo." (PMID 36765733, 2023). "FISH detection of USP6 rearrangement will be valuable for clarifying the diagnosis, and the method of surgery can be determined according to the tumor size, location, and follow-up." (PMID 36727055, 2022). "Seemingly it is controversial that the mRNA level of USP6 was increasing with time (p = 0.047), but presumably, in “old” NF, the fewer USP6 split-signal harboring tumor cells produced more mRNA as in the “young” ones." (PMID 34381187, 2021). "In this context, RNA-sequencing analysis of OS cells and mesenchymal stem cells differentiated or not differentiated into osteoblasts reveals increased expression of four USPs in OS tumor cells: USP6, USP27x, USP41 and USP43." (PMID 34571917, 2021). "Immunohistochemistry confirmed that USP6 overexpression was characteristically confined to tumor cells harboring USP6 split signals." (PMID 34381187, 2021). "In these scenarios, TNC is functioned as a strong promoter, leading to activation of oncogenes NRG1 and USP6, and subsequently induction of tumor formation." (PMID 34256767, 2021). "There was only one tumor suppressor (CSF2) and one cancer census gene in Cluster 3 (USP6); there are four tumor suppressors (GALR1, IRF4, PTPRT and SOX11) and one more cancer census gene in Cluster 4 (NRG1)." (PMID 28198667, 2017). "All of these findings suggest that JAK-STAT3 is activated in neoplasms with USP6 translocation and that focusing on this pathway could be a useful strategy for reducing the growth of tumors caused by overexpression of USP6." (PMID 40348771, 2025). "However, a USP6 gene rearrangement study is of help in differentiating them because ABC is a true neoplasm-inducing USP6 gene rearrangement." (PMID 38335421, 2024). "However, since ABC is a true neoplasm that results in USP6 gene rearrangement, a USP6 gene rearrangement study is helpful for differentiation." (PMID 39312383, 2024). "In contrast, USP6 retained the ability to suppress tumor growth in mice treated with control IgG2a." (PMID 37615015, 2023). "Remarkably, the RUNX2 gene has been discovered by next generation sequencing to be one of the fusion partners of the gene encoding ubiquitin-specific peptidase 6 (USP6), possibly contributing to the osteoblastic as well as osteolytic features of this neoplasia." (PMID 37509363, 2023). "However, the detection of a ubiquitin-specific protease (USP6) gene translocation within some ABCs has moved them towards the group of “true” neoplasms." (PMID 37686534, 2023). "Here, we demonstrate an essential role for NK cells in USP6-mediated tumor suppression." (PMID 37615015, 2023). "Depletion of NK cells reversed the tumor-inhibitory effects of USP6." (PMID 37615015, 2023). "Although such cases are limited, the possibility of some crossover or even transition between USP6-associated neoplasms cannot be ruled out." (PMID 36727055, 2022). "In addition, individual USP6 fusion partners that overlap between these tumor subtypes have been identified." (PMID 36727055, 2022). "In the present study, by comparing the expression of the 56 USPs described in the literature, in seven OS cell lines and in mesenchymal stem cells or osteoblasts, we identified four USPs: USP43, USP41, USP27x and USP6, with increased expression in OS tumor cell lines." (PMID 34571917, 2021). "Other notable findings in this tumour included missense variants in NFKB2, NF2 and USP6." (PMID 37435187, 2021). "Notably, proliferative myofibroblasts/fibroblasts with or without osteoid component metaplasia are characteristics of USP6-associated neoplasms." (PMID 40348771, 2025).
tumor (continued). "In this context, elevated expression of four USPs (USP6, USP27x, USP41, and USP43) in OS tumor cells has been revealed by RNA-sequencing investigation of OS cells and mesenchymal stem cells that have developed into osteoblasts or not." (PMID 40348771, 2025). "Primary ABC has been proposed to be a true neoplasm as it contains rearrangements of CDH11 and USP6 genes." (PMID 39462411, 2024). "Only six genes were present in both tumor initiation and tumor evolution stage: MUC4, MUC16, USP6, BCLAF1, KMT2C, and NOTCH2." (PMID 34918496, 2022). "Gathering all this information together, it is evident that with time, the number of those tumor cells harboring USP6 fusions are decreasing; suggesting some negative feedback mechanism triggered by USP6 fusion/overexpression." (PMID 34381187, 2021). "Additionally, several other genes associated with poor prognosis in other cancers were upregulated in TAS but downregulated in tumor of BA vs WA patients including oncogene SOX4 and USP6." (PMID 34316327, 2021). "After a fairly long debate, NF was considered as a true neoplasm and not as an inflammatory reactive lesion due to its consistent USP6 gene rearrangement; the most common is the MYH9-USP6 fusion." (PMID 34381187, 2021). "Notably, USP6 rearrangements are absent in ABC-like changes arising secondarily within other tumor." (PMID 41263005, 2025). "Results of immunostainings, along with qRT-PCR results, favored the previously-suggested USP6-induced negative feedback mechanism through activation of TRAIL and IFN-beta, likely resulting in apoptosis and senescence of tumor cells harboring USP6 fusions." (PMID 34381187, 2021).
cancer (21 papers, 2008 to 2026). A tumor composed of atypical neoplastic, often pleomorphic cells that invade other tissues. "Differential diagnosis included ABC which can be a primary, de novo neoplasm characterized by rearrangements of the USP6 gene, or secondary, arising in association with other benign or malignant tumors, including GCTB." (PMID 27630783, 2016). "One of the most striking features of USP6 in the context of cancer is its involvement in chromosomal translocations." (PMID 40348771, 2025). "When FT385 was evaluated against other DUBs, it solely inhibited USP6 at 200 nM in the case of cancer cells, indicating great selectivity in inhibiting the cleavage of Ub-Rho110 at 1 nM IC50." (PMID 40348771, 2025). "The overactive USP6 protein promotes cell survival, proliferation, and resistance to apoptosis, all of which are significant features of cancer growth." (PMID 40348771, 2025). "For P11, there were two nonsynonymous mutations (USP6 and PABPC1) shared by two tumors, both of which were cancer-related mutations." (PMID 35171361, 2022). "We also noted seven genes marked with “caution” in PeCanPIE showing the truncation close to the C-terminal (CUX1, FLCN, FLG, MSH6, NSD1, PRDM9, and USP6), questioning its functional effects in the cancer context." (PMID 35406420, 2022). "Mutations in cancer-related genes (KMT2C, NOTCH2, PRKAR1A, SDHA, and USP6) and genes related to EC (ARID1A, CTNNB1, PIK3CA, and PTEN) were identified with high frequencies among the three samples." (PMID 35626111, 2022). "These eight transcripts were linked to the following cancer‐related genes: TRIM33, USP6, PRDM16, SETD1B, MLLT3, KEAP1, CHD2, and DCAF12L2." (PMID 32821278, 2020). "Emerging research has revealed novel physiological roles for USP6 in cancers and other diseases." (PMID 40348771, 2025). "A wide expression of USP6 is seen in several human cancer types." (PMID 40348771, 2025). "Furthermore, BC18 and descendant cells had mutations in the cancer-related genes (in PDE4DIP, as well as a back mutation in MTOR, and USP6) in comparison to normal cells, which may have contributed to turning this lineage into an active cancer line." (PMID 35951662, 2022). "Discovering a deubiquitylating enzyme that can interact, stabilize or deubiquitylate USP6 is of high significance, because inhibitors against the newly identified deubiquitylating enzyme which regulates USP6 might affect USP6 protein level and its role in cancer progression." (PMID 28659380, 2017). "In our study, we have compared top DASE loci identified in our genome-wide ASE studies with the current cancer genome database provided by Cancer Gene Census (Sanger Institute) and have identified two DASE loci (USP6 and ZNF331) listed as cancerous genes." (PMID 23107584, 2012). "Nevertheless, our evidence now indicates that USP6 and PARP-1 should be considered important factors in the responsiveness of cancer cells to radiation therapy, particularly proton beam therapy that can generate high-LET protons and CDD at the distal end of the Bragg peak." (PMID 30851349, 2019).
adenocarcinoma of the (1 paper, 2025). "Patient EOCRC#44 who carries HVs in both HSB3B2 and USP6 genes presented with adenocarcinoma of the ascending colon at the age of 36 and his father was reported with CRC (unknown age at diagnosis)." (PMID 40429818, 2025).
infection (1 paper, 2018). The state of being infected such as from the introduction of a foreign agent such as serum, vaccine, antigenic substance or organism. "Overexpression of host ubiquitin-specific protease 6 (USP6), referred to here as TRE17, is sufficient to reverse the retention of ARF6 and of some, but not all, CIE cargos in the context of infection." (PMID 30042195, 2018).
neurodegenerative disease (1 paper, 2019). A disorder of the central nervous system characterized by gradual and progressive loss of neural tissue and neurologic function. "Based on our findings here, it will be interesting to determine the specific role of USP6-mediated protein turnover in neurodegenerative disease." (PMID 31841517, 2019).
USP6 also shares sentences with these, for which no sentence is quoted: colorectal cancer (4 papers); bone cysts (2); ovarian carcinoma (2); Anxiety (1); autism spectrum disorder (1); benign tumors (1); breast tumours (1); cardiovascular disease (1); chondroblastoma (1); chondromyxoid fibroma (1); Chronic Myeloid Leukemia (1); dermatofibrosarcoma protuberans (1); desmoid fibromatosis (1); diabetes (1); Epileptic encephalopathy (1); extraskeletal myxoid chondrosarcoma (1); glaucoma (1); HCMV infection (1); head and neck squamous cell carcinoma (1); hearing loss (1); inflammatory myofibroblastic tumor (1); Insulin resistance (1); Intellectual disability (1); intellectual impairment (1); lipoblastoma (1); liposarcoma (1); lymphoma (1); malignant peripheral nerve sheath tumor (1); mesenchymal chondrosarcoma (1); mesenchymal neoplasms (1).
A further 11 diseases each share a sentence with USP6 in 1 paper.